SNORD3H (small nucleolar RNA, C/D box 3H)
Gene: Small nucleolar RNA gene on chromosome 8 (97,358,265 to 97,358,478, forward strand). Ensembl gene ENSG00000207215.
Gene Ontology:
Biological process: RNA processing
Cellular component: nucleolus
Homologues: Orthologues: chimpanzee U3 (99% identical), macaque U3 (84% identical). Paralogues in human: U3 (83% identical), SNORD3P1 (83% identical), U3 (82% identical), SNORD3E (79% identical), SNORD3G (79% identical), U3 (78% identical), SNORD3D (77% identical), U3 (77% identical), U3 (76% identical), U3 (75% identical), U3 (74% identical), U3 (73% identical), and 10 more.